IL6 (interleukin 6)
Diseases named in the same sentence as IL6 in open-access papers (continued):
Sharing a sentence is not in itself a finding about the gene and the disease.
anterior uveitis (4 papers, 2022 to 2024). Inflammation of the iris and anterior chamber of the eye. "In humans with anterior uveitis, specific pro-inflammatory cytokines have been detected in aqueous humor (AH) including Interleukin (IL)-6, IL-8, IL-10, IL-13, IL-17, interferon-gamma (IFNγ), and tumor necrosis factor-alpha (TNFα)." (PMID 35998207, 2022). "This is in agreement with previous studies that showed an increase of IL-6 in the anatomical types of anterior uveitis." (PMID 35061677, 2022). "The current study demonstrates that IL-4, IL-6, IL-18, and TNFα have the potential to be relevant in dogs with post-phaco anterior uveitis." (PMID 35998207, 2022). "Also, IL-4, IL-6, IL-18, and TNFα may be important pro-inflammatory cytokines in dogs with anterior uveitis and POH following phacoemulsification (‘POH group’)." (PMID 35998207, 2022). "A slight upregulation of the IL1β and downregulation of IL6, IL4, and CD11b further confirmed a basal complement activation in the blood of patients with anterior uveitis." (PMID 38187376, 2023). "Dogs with anterior uveitis and POH following phacoemulsification surgery express elevated levels of IL-4, IL-6, IL-18 and TNFα in AH, which is consistent with the human literature." (PMID 35998207, 2022).
aortic valve calcification (4 papers, 2021 to 2023). "Our results agree with the identification of IL6 as a locus risk for stenosis and also with the intervention of this cytokine in aortic valve calcification." (PMID 36337884, 2022). "IL-6 expression is elevated in human calcific aortic valve disease, and phosphate-induced valve mineralization chiefly relies on IL-6 expression." (PMID 33593281, 2021).
aortic valve disease (4 papers, 2011 to 2026). "VEC5 also had the highest expression of IL6, which has been identified by genome-wide association studies as being upregulated in aortic valve disease." (PMID 39766890, 2024). "Patients with aortic valve disease were genotyped for PALMD rs6702619, LPA rs10455872, and IL6 rs1800795 polymorphisms and circulating levels of interleukin-6 (IL-6) were measured." (PMID 36337884, 2022). "Our results show that elevated pressure induces a gene expression pattern in cells that is considerably similar to that seen in aortic valve disease, in terms of altered expression of ECM proteins (MMP-1, MMP-3) and proinflammatory cytokines (IL-1β, IL-6)." (PMID 21876831, 2011).
aspiration pneumonia (4 papers, 2010 to 2024). "In our patient, TCZ suppressed IL-6 as well as the early inflammatory symptoms of aspiration pneumonia." (PMID 24872899, 2014). "Aspiration pneumonia induces muscle atrophy in the respiratory, skeletal, and swallowing systems via the expression of pro-inflammatory biomarkers such as C-reactive protein and IL-6." (PMID 39311243, 2024).
atrial flutter (4 papers, 2014 to 2025). A disorder characterized by an electrocardiographic finding of an organized, regular atrial rhythm with atrial rate of 240-340 beats per minute. "In addition, a prospective study on patients with atrial flutter also found that after radical ablation, the levels of CRP (6.28 mg/L vs. 2.92 mg/L, p = 0.028) and IL-6 (p = 0.002) in patients with atrial flutter significantly decreased." (PMID 40709209, 2025). "In addition, previous studies showed that C-reactive protein and IL-6 serum levels were significantly decreased in patients with atrial flutter after successful ablation." (PMID 38988665, 2024). "In atrial flutter patients, the level of IL-6 was higher in peripheral blood than in blood taken from the coronary sinus, indicating a potentially systemic response, with IL-6 level decreasing over time after ablation." (PMID 38256155, 2024).
autonomic neuropathy (4 papers, 2013 to 2025). An inherited or acquired peripheral neuropathy affecting the autonomic nervous system. "A pro-inflammatory immunotype defined by elevations in type 1 cytokines (IL-6, IL-17) and increased numbers of CD8+ T-cells was associated with autonomic neuropathy characterized by deficits in sympathetic nervous system activity (aOR=4.7, p=0.017)." (PMID 39464041, 2025). "It appears that IL‐6 is likely to play a central mechanistic role, whereby its levels also correlate with manifestations, such as autonomic neuropathy and hence the partial uncoupling of the cardiac pacemaker from autonomic control." (PMID 35439350, 2022). "Second, a pro-inflammatory immunotype defined by elevations in type 1 cytokines (IL-6, IL-17) and increased numbers of CD8 + T-cells was associated with autonomic neuropathy characterized by deficits in sympathetic nervous system activity (aOR = 4.7, p = 0.017)." (PMID 39764146, 2024).
B-cell acute lymphoblastic leukemia (4 papers, 2021 to 2026). A neoplasm of lymphoblasts committed to the B-cell lineage, typically composed of small to medium-sized blast cells. "Here the authors show that tumor microenvironment-derived IL-6 promotes resistance to doxorubicin by suppressing CD8 T cell anti-tumor immune responses in a preclinical model of B-cell acute lymphoblastic leukemia." (PMID 34711820, 2021). "Using a mouse model of BCR-ABL+ B-cell acute lymphoblastic leukemia, we show that chemotherapy-induced anti-cancer immunity is suppressed by the tumor microenvironment through production of the cytokine IL-6." (PMID 34711820, 2021).
CADASIL (4 papers, 2023 to 2025). "The profound increased expression of ICAM-1 and IL-6 in vitro in VSMCs also supports the hypothesis that there is a unique inflammatory response in many arterioles in CADASIL." (PMID 37158955, 2023). "Previous studies have detected systemic inflammatory cytokines, including IL-1β, IL-6, TNF-α, CCL2, and CXCL16, and found that their expression levels were significantly elevated in CADASIL patients, which is consistent with our results." (PMID 41000387, 2025). "The serum inflammatory cytokines were analyzed by ELISAs and revealed that the levels of serum IL-1β, IL-6, TNF-α, CCL2, and CXCL16 were significantly elevated in the patient group compared with their family members, suggesting a systemic inflammation in CADASIL patients." (PMID 37684694, 2023).
cardiac interstitial fibrosis (4 papers, 2016 to 2024). "Interleukin 6 (IL-6) has been shown to be an important regulator of cardiac interstitial fibrosis." (PMID 26972749, 2016).
cervical intraepithelial neoplasia (4 papers, 2021 to 2025). "Similarly, IL-6 and IL-8 levels measured in cervicovaginal washings are higher in patients with invasive CC than in those with cervical intraepithelial neoplasia." (PMID 40003544, 2025). "This study therefore estimated and compared the levels of circulatory IL-4, IL-6, IL-10, TNF-α, and IFN-γ cytokines among adult women identified to have different grades of cervical intraepithelial neoplasia (CIN) and with cervicovaginal infection." (PMID 37635942, 2023).
channelopathy (4 papers, 2022 to 2025). Channelopathies are a group of diseases caused by the dysfunction of ion channel subunits or their interacting proteins. "Noteworthy is that Piezo2 channelopathy is also suggested to be linked to the TLR4/IL-6/TNF-α pathway." (PMID 37895134, 2023). "Accordingly, Piezo2 channelopathy, which has been suggested to be associated with IL-6 increases through the Hsp70/TLR4/Myd88/IL-6 pathway, as in DOMS, could lead to an imbalanced ratio of Th17/Treg in RA, therefore paving the way to the autoimmune response." (PMID 37108693, 2023). "It is noteworthy that the involvement of heat shock protein 70 (Hsp70) activation through the Hsp70/TLR4/Interleukin-6/TNF-α pathway is implicated in DOMS and theorized as the route to Piezo2 channelopathy." (PMID 40863771, 2025). "There is increasing experimental evidence supporting the effects of inflammatory cytokines (mainly tumor necrosis factor-α (TNF-α), interleukin-1β (IL-1β), and interleukin-6 (IL-6)) on cardiac ion channels, and this specific type of channelopathy is termed inflammatory cardiac channelopathy." (PMID 35711306, 2022). "Hence, Piezo2 channelopathy on somatosensory terminals contributing to proprioception could not only activate the innate immune system through IL-6 but also activate the adaptive immune system in RA." (PMID 37108693, 2023).
chickenpox (4 papers, 2016 to 2024). A contagious childhood disorder caused by the varicella zoster virus. "There are many similarities in pathogenesis between certain poxviruses and chickenpox, including a viremia with a cellular stress response leading to high levels of the IL-6 cytokine." (PMID 36560805, 2022). "Prognosis of the development of severe and complicated forms of chickenpox can be based on the insufficiently increased (less than two normal values) levels of IL-6 and IFN-γ, induced chemiluminescence, CD16, and CD20." (PMID 34795992, 2021). "Both mRNA and protein levels of IL-6 and IL-8 were increased during acute varicella 3 DPI." (PMID 27677639, 2016). "Conversely, an insufficient increase (less than double-normal values) in IL-6, IFN-γ, ICL, CD16, and CD20 is predictive of severe and complicated forms of chickenpox." (PMID 34795992, 2021).
cholangitis (4 papers, 2012 to 2025). An acute or chronic inflammatory process affecting the biliary tract. "In the follow-up study of cholangitis in this mouse model, we expanded this colony by intercrossing hemizygous TGFβRII IL-6−/− litters." (PMID 23145171, 2012).
cholelithiasis (4 papers, 2023 to 2025). The presence of crystallized deposits forming in the gallbladder or biliary tree, primarily composed of cholesterol, bilirubin, and bile. "Here, our single-cell transcriptome analysis observed that HLF levels were markedly up-regulated in cholelithiasis tissues and were enhanced upon IL-6 stimulation." (PMID 40779629, 2025). "Furthermore, increased levels of IL-6 have been observed in patients with cholelithiasis." (PMID 37444550, 2023).
Cholestatic liver disease (4 papers, 2013 to 2021). "We have recently shown that the cytokine IL-6 and the cytokine-inducible transcription factor STAT3 protect from cholestatic liver injury and fibrosis in the Mdr2−/− mouse model for cholestatic liver disease." (PMID 27568040, 2017). "Hepatoprotective functions of STAT3 signaling in cholestatic liver disease have been investigated in mice lacking STAT3, IL-6, gp130, or express pathway specific gp130 mutants." (PMID 27568040, 2017).
choroidal neovascularization (4 papers, 2012 to 2023). An eye disorder described by the growth of new blood vessels that originate from the choroid through a break in the Bruch membrane into the sub–retinal pigment epithelium (sub-RPE) or subretinal space. "Interleukin 6 is a potent stimulator of vessel sprouting and angiogenesis, and IL6 RNA levels have been previously shown to increase in choroidal macrophages in a laser model of choroidal neovascularization in mice." (PMID 37878301, 2023). "In addition to VEGF, choroidal neovascularization (CNV) involves a number of angiogenic molecules and inflammatory cytokines: interleukin-6 (IL-6), interleukin-8 (IL-8), intercellular adhesion molecule-1 (ICAM-1), and monocyte chemoattractant protein-1 (MCP-1)." (PMID 25110587, 2014).
Chronic diarrhea (4 papers, 2021 to 2025). The presence of chronic diarrhea, which is usually taken to mean diarrhea that has persisted for over 4 weeks. "A trial on chronic diarrhea in humans reported that modulation of intestinal inflammation via IL-6 inhibition improved the symptoms." (PMID 35631156, 2022). "Our data also suggested that FMT intervention obviously increased the level of IL-10 and decreased the levels of IL-6, IL-8, IL-1β, and IFN-γ in chronic diarrhea monkey serum during the intervention, especially on Day-8." (PMID 36551772, 2022). "Chronic diarrhea in IBD results from intestinal barrier dysfunction, increased permeability, and electrolyte absorption impairment, all of which are exacerbated by pro-inflammatory cytokines such as TNF-α and IL-6." (PMID 40299351, 2025). "Therefore, the reduction of IL-6 in patients with chronic diarrhea by L. plantarum CCFM1143 treatment was not significant, which may be related to the number of viable Lactobacillus taken and the duration of treatment." (PMID 34721416, 2021).
coccidiosis (4 papers, 2018 to 2024). A parasitic infection caused by Coccidia. "The objective of this study was to provide a basis for validating the influence of SNPs on IL-6 gene expression and the association between SNPs and coccidiosis resistance in Jinghai yellow chickens." (PMID 30200658, 2018). "In coccidiosis, there is increased synthesis of proinflammatory cytokines such as IL-1β, IL-6, and TNF-α, which further disrupt the TJ barrier and amplify the inflammatory process by allowing more luminal antigens to permeate." (PMID 37763330, 2023). "These predictions provide a basis for further study of the regulation of IL-6 expression and its relationship to chicken coccidiosis." (PMID 30200658, 2018).
Cushing syndrome (4 papers, 2019 to 2025). Cushing's syndrome (CS) encompasses a group of hormonal disorders caused by prolonged and high exposure levels to glucocorticoids that can be of either endogenous (adrenal cortex production) or exogenous (iatrogenic) origin. "Patients with active or treated Cushing syndrome exhibit elevated inflammatory markers, including C-reactive protein (CRP), interleukin-6 (IL-6), and tumor necrosis factor-alpha (TNF-α)." (PMID 40729034, 2025). "Conversely, the immunosuppressive properties of GCs may attenuate intrahepatic low-grade chronic inflammation, largely mediated by interleukin-6 (IL-6), which could partly explain the relatively low prevalence of MASLD reported in overt Cushing syndrome in some studies." (PMID 41153782, 2025).
cutaneous squamous cell carcinoma (4 papers, 2017 to 2024). "Their another work in investigating the prognostic role of IL-6 among patients with advanced cutaneous squamous cell carcinoma found both high serum levels of IL-6 at baseline and increase after PD-1 blockade immunotherapy predict unfavorable prognosis." (PMID 38430269, 2024). "Serum levels of IL-6 at baseline and changes after cemiplimab immunotherapy may have a prognostic significance in patients with advanced cutaneous squamous cell carcinoma." (PMID 36823670, 2023). "This could partly be caused by increased IL6 expression mediated by UV-exposure since in cutaneous squamous cell carcinoma IL6 has been shown to be tumour-promoting by induction of CAFs." (PMID 28987144, 2017).
deafness (4 papers, 2014 to 2024). An inherited or acquired condition characterized by the complete loss of the ability to hear from one or both ears. "Beyond mouse experiments, TNF-α and IL-6 levels were significantly higher in the perilymph fluid of humans with deafness." (PMID 35010640, 2021). "These mice exhibited increased Cav1.3 channel currents, enhanced exocytosis, and reduced synapses numbers in IHCs compared to the “improved hearing” IL‐6 KO 9 M IH mice, suggesting that Cav1.3 upregulation may play an important role in deafness." (PMID 39148148, 2024). "In noise-induced deafness, proinflammatory cytokines or chemokines, including TNF-α, IL-1β, IL-6, Icam-1, and Ccl2, were increased in cells of the stria vascularis or lateral wall." (PMID 33505961, 2020). "IL‐6 up‐regulation of Cav1.3 channels via the JAK‐MAPK pathway contribute to neurotransmitter excitotoxicity and synaptic impairment in the cochlea of mice with deafness." (PMID 39148148, 2024). "The expression of IL-6 and CCL-2 was higher in the permanent hearing damage model than in the temporary hearing damage model, suggesting that the inflammatory response is a potential therapeutic target for the treatment of deafness resulting from energy failure in the lateral cochlear wall." (PMID 24614528, 2014).
diabetic ketoacidosis (4 papers, 2016 to 2025). The metabolic condition resulted from uncontrolled diabetes mellitus, in which the shift of acid-base status of the body toward the acid side because of loss of base or retention of acids other than carbonic acid is accompanied by the accumulation of ketone bodies in body tissues and fluids. "The pro-inflammatory cytokines (IL-6 and TNF-alpha) in diabetic ketoacidosis regulate the expression of vascular endothelial growth factor, ultimately increasing vascular permeability, which then causes the vasogenic cerebral edematous changes seen in PRES." (PMID 34840779, 2021).
diphtheria (4 papers, 1996 to 2024). A Gram-positive bacterial infection caused by Corynebacterium diphtheriae. "A variety of factors, such as the mycobacterial heat shock proteins in BCG and diphtheria toxoid in BCG, tetanus–diphtheria, and influenza vaccines, can induce IL-6 associated with the generation of Th17 cells." (PMID 39200759, 2024). "After subcutaneous injection in patients, IM showed immunomodulatory effects, as manifested by decreasing levels of interleukin-6 (IL-6) and tumor necrosis factor (TNF) in response to diphtheria toxoid vaccination." (PMID 32585846, 2020). "Mice which had received all three shots of Infanrix® IPV and were sacrificed 7 days after the third shot had significantly more diphtheria-specific CD4+ T cells producing IL-2, IL-6, or TNF-α when treated with GM-CSF than placebo-treated controls." (PMID 29961602, 2018). "The effect of vaccination with diphtheria toxoid (AD-M) on TNF and IL-6 production has been studied in humans." (PMID 18475748, 1996).
Dyskinesia (4 papers, 2024 to 2025). A movement disorder which consists of effects including diminished voluntary movements and the presence of involuntary movements. "The study’s findings showed that, in PD patients with dyskinesia, IL-6 levels were significantly elevated (p < 0.05) compared to the controls." (PMID 38392998, 2024). "Patients with dyskinesia exhibited notably higher IL-6 levels compared to controls, and TNF-α was significantly elevated in both PD patient groups relative to the control group." (PMID 38392998, 2024). "At the same time, increased cytokines play a role in the dyskinesia that occurs in PD, and these are molecules such as TNF-α and IL-6." (PMID 40464816, 2025). "In the non-dyskinesia group, a significant negative correlation at p < 0.05 was found between IL-6 and 25(OH)-vitamin D (R = −0.44)." (PMID 38392998, 2024). "A study has revealed that elevated levels of IL-6 and TNF-α in Parkinson’s disease (PD) patients, along with alterations in visfatin and progranulin levels between PD patients with and without dyskinesia, indicate significant changes in inflammatory biomarkers and adipokines in PD." (PMID 40464816, 2025). "The aim of this study was to compare the levels of certain analytes, including IL-6, TNF-α, CRP, visfatin, progranulin, and 25(OH)-vitamin D, across three distinct groups, namely PD patients without dyskinesia, PD patients with dyskinesia, and healthy controls." (PMID 38392998, 2024).